IL6 (interleukin 6)
Diseases named in the same sentence as IL6 in open-access papers (continued):
Sharing a sentence is not in itself a finding about the gene and the disease.
Sepsis (continued). "In murine CLP-sepsis, human adipose-derived mesenchymal stem cells were able to modulate sepsis by downregulation of Th1-cell responses, associated with lower levels of pro-inflammatory cytokines (TNF, IL-1β, IL-6, IL-12, IFNγ) and higher levels of anti-inflammatory IL-10 derived from macrophages." (PMID 31114571, 2019). "Concentrations of IL6 and TNFα are typically elevated during infections and sepsis." (PMID 31121841, 2019). "While LPS-induced sepsis in these mutants could be counteracted by application of an IL-1R antagonist, the results presented here revealed that anti-IL-6 antibody treatment reduced disease severity and mortality in a mouse model of aGvHD." (PMID 29643984, 2018). "Serum procalcitonin (PCT) and interleukin-6 (IL-6) have been reported as diagnostic markers of sepsis, while they are unfortunately expensive or not readily available as ideal biomarkers." (PMID 29706801, 2018). "Likewise, plasma IL-6 has been shown to be positively associated with mortality in acute heart failure and with AKI in patients with sepsis." (PMID 29344362, 2018). "Sepsis is one of the most common causes of ALI, with LPS being the most important biological mediator as they induce the secretion of inflammatory cytokines, such as TNF-α, IL-1β, and IL-6 in response to bacterial toxins." (PMID 30083155, 2018). "In addition, the inhibition of lipogenesis or the increase in lipid oxidation reduces levels of free fatty acids, TNF-α, and IL-6, and reduces liver injury improving survival in sepsis." (PMID 29760707, 2018). "Lowering the expression of another miRNA, miR-223, was associated with an increase in neutrophil infiltration and myocardial dysfunction in a sepsis patient via activation of STAT3/IL6 and Sema3, indicating that the presence of the miR-223 prevents this influx and lowers inflammation." (PMID 30523422, 2018). "Among the various cytokines tested, IL-6 is a key mediator of the inflammatory response of sepsis." (PMID 30374077, 2018). "We previously reported that treatment of mice with MTA before infection with a lethal dose of S. Typhimurium resulted in reduced production of sepsis-related cytokines (interleukin-6 [IL-6] and tumor necrosis factor alpha [TNF-α]) and modestly prolonged survival." (PMID 29866910, 2018). "In healthy adults without an ongoing inflammatory process, the IL-6 concentration ranged from 0.2 to 7.8 pg/mL, whereas the IL-6 concentration in adults with sepsis could be > 1600 pg/mL." (PMID 30400775, 2018). "We used a random-effects model to detect IL-6 for neonatal sepsis with PROM." (PMID 30461611, 2018). "EGL decreases in response to elevatied IL-6 levels during sepsis and trauma." (PMID 30078997, 2018). "Experimental studies of sepsis showed beneficial effects of hyperosmolar solutions modulating inflammatory response, as for instance the expression and release of cytokines TNFα and IL-6." (PMID 29445877, 2018). "In the current study, we observed significant relationships between plasma levels of MCP-1, sCD14, HBP, and cortisol and the source of sepsis, whereas the well-established inflammatory cytokines (i.e., IL-6 and IL-10) demonstrated relatively low detectability in our cohort of septic patients." (PMID 29769838, 2018). "IL-6 has been used as a biomarker for sepsis since baseline plasma levels ranging between 1 and 5 pg mL− 1 may increase million-fold during sepsis." (PMID 30041663, 2018). "We determined to find out if reductions in the plasma concentrations of the cytokines tumor necrosis factor (TNF)-α, IL-6, and IL-10, and the rate of change of IL-6 at 24 h after ICU admission were survival predictors for patients with sepsis and septic shock at an ICU in Ho Chi Minh City, Vietnam." (PMID 30400775, 2018). "XBJ normalized TNFα and IL-6 production in rodent sepsis models." (PMID 30618740, 2018).
Sepsis (continued). "The levels of TNF-α, IL-6 and IL-10 were significantly higher in the miR-31 mimic group (all p < 0.05) while significantly lower levels were observed in the miR-31 inhibitor group when compared with the sepsis group (all p < 0.05)." (PMID 30340459, 2018). "Thus, in the present study, the inhibition of let-7a-5p resulted in significantly increased concentrations of TNF-α, IL-1β, IL-6, and iNOS and decreased hepatic function in mice with sepsis." (PMID 29599918, 2018). "However, the induction of pro-sepsis cytokine IL-6 is significantly higher in lymphocytes, when activated by SECepi (p ≤ 0.01)." (PMID 29584685, 2018). "The observed increase in IL-6 levels following saline resuscitation in septic animals and its association with increased AKI risk provide an additional explanation for renal dysfunction during sepsis resuscitation treatment." (PMID 29589205, 2018). "The TNF-α, IL-1β, and IL-6 concentrations in patients with sepsis were markedly greater compared to those in the controls, and the levels also increased with the development of sepsis." (PMID 30268141, 2018). "Therefore, we evaluated the effects of pilloin on TNF-α and IL-6 levels in an LPS-induced sepsis model." (PMID 30513815, 2018). "IL-6-inhibitors, such as the humanized monoclonal antibody (tocilizumab), are approved for the treatment of rheumatoid arthritis, but beneficial effects of cytokine-blockade drugs to improve outcome in sepsis has yet to be demonstrated." (PMID 30041663, 2018). "The results showed that IL-6 reduction at the level of ≥86% at 24 h from ICU admission could be a survival predictor for our patients with sepsis and septic shock." (PMID 30400775, 2018). "Moreover the chemokines interleukin-8 (IL-8) and monocyte chemoattractant protein-1 (MCP-1) have been shown to be superior to IL-6 for diagnosis of sepsis and prediction of sepsis mortality respectively." (PMID 30233566, 2018). "Importantly, the rise of serum IL-10 along with IL-6 and IL-8 is part of a combined proposed predictor score for fatal outcomes in human sepsis, and MEDI3902 administration in the present study resulted in downregulation of all three transcripts." (PMID 29483116, 2018). "We found that, in a previous study, exogenous Cit alleviated the release of proinflammatory cytokines (TNF-α, IL-1β, and IL-6) in early sepsis and increased the release of late-stage anti-inflammatory cytokines (IL-4 and IL-10) to alleviate the inflammatory response of septic rats." (PMID 30498752, 2018). "Notably, the in vitro LPS-stimulated experiment showed that the sepsis-associated AA risk genotype significantly increased TNF-α and IL-6 secretion in PBMCs upon exposure to LPS in vitro." (PMID 30268141, 2018). "In our study, we found that AA decreased levels of interleukin-1β (IL-1β), IL-6, alanine aminotransferase and blood urea nitrogen in serum; attenuated liver, lung and kidney damage; and improved the survival among mice with experimental sepsis." (PMID 29599924, 2018). "Interestingly, sepsis groups demonstrated a significant elevation in creatinine, IL-6 and IL-10 when compared to hour-adjusted control groups, thus indicating a possible dysfunction of more organs including the kidneys." (PMID 29136027, 2017). "IL-6 can be produced and released by T cells and macrophages and is considered to be a clinical marker of severe sepsis that could lead to high morbidity and mortality." (PMID 28993690, 2017). "Apart from TNF-α, it also has been documented that other pro-inflammatory cytokines such as IL-6 could increase significantly in sepsis patients." (PMID 29207683, 2017). "Some studies considered IL-6 an indicator for sepsis or for predicting outcome and mortality." (PMID 28484510, 2017). "Moreover, a correlation between sepsis severity and serum levels of IL-6 and PCT had been observed previously." (PMID 28380034, 2017).
Sepsis (continued). "On the one hand, in some studies was found that SP could play a role in the inflammatory response to sepsis by the release of pro-inflammatory cytokines as IL-1, IL-6, and TNF-α." (PMID 28714876, 2017). "Furthermore, blocking IL-6 signaling at an early stage of sepsis provided a therapeutic benefit; consistently septic patients with a lower serum IL-6 concentration showed a low mortality risk." (PMID 28661460, 2017). "In murine sepsis models, blockade of IL-6 trans-signaling was sufficient to rescue mice from death." (PMID 28714885, 2017). "Studies have shown that exaggerated IL-6 levels can lead to an acute severe systemic inflammatory responses and subsequent sepsis because of the activation of the coagulation pathway and vascular endothelial cells along with the inhibition of myocardial function." (PMID 28493985, 2017). "There is a significant body of evidence that concentration of TNF-α and IL-6 is increased in BALF of patients with ARDS, and the persistent elevation of pro-inflammatory cytokines has been associated with a worse outcome in patients with ARDS or sepsis." (PMID 28486961, 2017). "Activation of the innate immune system by sepsis produces pro-inflammatory cytokines (TNFα, IL-1β and IL-6) that may trigger muscle wasting." (PMID 28883493, 2017). "Although increased IL-6 levels indicate adverse clinical outcomes in adults with sepsis/septic shock, implementing of IL-6 measurement in routine diagnostic work up was not shown to improve patient-centered clinical outcomes." (PMID 29063386, 2017). "This study demonstrates an association between significant cardiac depression by SE and increase in expression of pro-inflammatory cytokines (TNF-α, IL-6, and IL-1β) further supporting the current literature regarding the role of pro-inflammatory cytokines in the development of myopathy in sepsis." (PMID 28405943, 2017). "Therefore, we combined CLP-induced sepsis with intermittent blood sampling monitoring the endogenous production of IL-6, TNF-α and IL-10 in rats over 72 h." (PMID 29204105, 2017). "Our present study differed from previous investigations using the animal models induced by stress, LPS or sepsis, where we directly determined hippocampal cytosol protein levels of IL-6, IL-1β, and TNF-α by using acute and chronic ketamine administration models." (PMID 28373844, 2017). "Only IL-6, IL-8, IL-10, and procalcitonin were useful as discriminators of sepsis." (PMID 28769538, 2017). "Likewise, decreased activation of IL-1β in Nlrp3 KO mice during sepsis resulted in decreased Il6 expression, which is a target of IL-1β and mediates atrophy." (PMID 28097512, 2017). "On the one hand, in some studies it was found that SP could play a role in the inflammatory response to sepsis by the release of pro-inflammatory cytokines as interleukin (IL)-1, IL-6, and tumor necrosis factor (TNF)-α." (PMID 28714876, 2017). "We determined the plasma concentrations of TNF-α, IL-6 and IL-1β to determine whether MCP-1 gene polymorphisms had any effect on the production of these related cytokines in the sepsis and control groups." (PMID 28472164, 2017). "Furthermore, the MCP-1 rs1024611 AG/GG and rs2857656 GC/CC genotype carriers exhibited significantly higher concentrations of TNF-α and IL-6 compared with the rs1024611 AA and rs2857656 GG genotype carriers among the sepsis patients." (PMID 28472164, 2017). "Indeed, TNF-α, IL-1β, IL-6 mRNA expressions in the kidney were found to be greatly enhanced at 6 hours after CLP which was regarded as the early stage of sepsis." (PMID 28430592, 2017). "IL-8, IL-6, IL-10, and procalcitonin are useful as early biomarkers of sepsis." (PMID 28769538, 2017). "Thus, this study provides a molecular link how mitochondrial dysfunction leads to IL-6 overproduction and poor prognosis of sepsis." (PMID 28549777, 2017). "The role of IL-6 as a marker to diagnose sepsis or predict outcomes has also been studied." (PMID 28484510, 2017).
Sepsis (continued). "Taken together, these findings suggested that WK2-16 with HDAC8 inhibition could abrogate MMP-9 and IL-6 production, possibly providing a novel therapeutic strategy of sepsis and systemic inflammation." (PMID 28661460, 2017). "In contrast, IL-10-mediated control of excessive production of TNF-α and IL-6, which drive the pathological effects of the ‘cytokine storm’ found in patients with sepsis and septic shock may on the other hand be beneficial." (PMID 28216665, 2017). "This study found that IL-12 was the most promising source of diagnostic aid, particularly in confirming neonatal sepsis, and that IL-6 was not as effective in predicting the condition." (PMID 28487810, 2017). "Moreover, it was also shown that a decrease in IL-6 secretion leads to a higher survival of mice with sepsis." (PMID 29078765, 2017). "However, the sensitivity and specificity of current biomarkers for the early diagnosis of sepsis, such as C-reaction protein (CRP), procalcitonin (PCT) and interleukin-6 (IL-6) are limited, as they have been implicated in other non-inflammatory processes." (PMID 29207683, 2017). "Importantly, the plasma concentrations of TNF-α and IL-6 were significantly increased in sepsis patients with rs1024611 AG/GG or rs2857656 GC/CC genotypes, accompanied by an upregulation of MCP-1." (PMID 28472164, 2017). "At 48 h, we saw an IL-6 increase in the sepsis group when compared with the control group." (PMID 29273091, 2017). "Additionally, the induction of sepsis was observed based on the elevated levels of the sepsis-associated marker C-reactive protein (CRP) and the pro-inflammatory cytokine IL-6 in the circulatory system in pigs with MRSA-infected wounds." (PMID 28177877, 2017). "Mortality in sepsis has been reported to correlate with the upregulation of IL-6." (PMID 29311915, 2017). "Moreover, several studies have investigated the validity of using IL-6 for early sepsis diagnosis and predicting mortality." (PMID 28549777, 2017). "Combining PTX-3 with established biomarkers, such as IL-6, might be of additional value for the discrimination of sepsis and septic shock." (PMID 28793880, 2017). "IL‐6 is a proinflammatory cytokine that increases in case of sepsis." (PMID 28553016, 2017). "Serum Interleukin-6 levels rise during sepsis and serve as a prognostic marker of disease outcome." (PMID 27115295, 2016). "Using our murine sepsis model, we found that IL-6 effectively predicted mortality." (PMID 27669150, 2016). "A previous study revealed that over-expression of PPARβ/δ could attenuate gene expression of TNFα, IL-1β and IL-6 in alveolar macrophages and played a protective role in sepsis-induced acute lung injury." (PMID 27023591, 2016). "The capacity of mast cells to produce IL‐6 is well established 1, 38 and it has also been shown that mast cell‐derived IL‐6 plays a critical role in various pathological processes, including a protective role in sepsis." (PMID 27042303, 2016). "This trend was also observed in serum IL-6 levels in a mouse sepsis model." (PMID 27303721, 2016). "Further mechanistic investigation is warranted to test whether high IL-8 and IL-6 levels can mediate kidney injury in the setting of neutropenia, and explain our findings of increased AKI risk among neutropenic patients with sepsis." (PMID 27431667, 2016). "IL-6 is a cytokine that generates an initial response to injury or infection; its levels rise significantly during early sepsis, and for this reason, it has been used for sepsis diagnosis and patient outcome prediction." (PMID 27287669, 2016). "In addition, CSE gene deletion not only attenuated sepsis associated activation of ERK1/2-NF-κB p65 signalling but also abolished the generation of cytokines TNF-α, IL-6, and IL-1β and chemokines MCP-1 and MIP-2α." (PMID 27518439, 2016).
Sepsis (continued). "It is unclear whether elevated G-CSF, IL-8, and IL-6 contribute to the organ dysfunction or increased shock observed in neutropenic sepsis, but these elevations in inflammatory mediators may be maladaptive." (PMID 27431667, 2016). "The observation that IL-6 levels were actually somewhat higher in FXI-/- mice than WT mice 24 hours post-CLP may indicate that sepsis-induced immune dysfunction was greater in WT mice than in FXI-/- mice." (PMID 27046148, 2016). "In addition to CRP and PCT, the proinflammatory cytokine IL-6 is often measured in the context of sepsis." (PMID 26761003, 2016). "Thus, we evaluated monocyte modulation during sepsis by simultaneously assessing their phagocytic activity, the generation of ROS and NO, and the production of inflammatory cytokines (IL-6 and TNF-α)." (PMID 26879814, 2016). "Demographic and clinical patient information were recorded on admission to the ICU with blood samples taken for C-reactive protein (CRP), procalcitonin (PCT), interleukin-6, white blood cell count, as well as body temperature, age and the sepsis-related organ failure (SOFA) score." (PMID 27287669, 2016). "In this work we demonstrate that these receptors control hepatic cytokine production and signalling during sepsis in vivo and that the thyroid hormone directly antagonizes IL-6 signalling in cultured hepatocarcinoma cells and macrophages, leading to reduced STAT3 transcriptional activity." (PMID 27484112, 2016). "Cytokines such as interleukin-2, interferon-alpha, and interleukin-6 are hypothesized to be the main mediators for increased capillary leak in acute inflammatory states like sepsis." (PMID 26908009, 2016). "Interleukin-6 (IL-6) is a marker of sepsis severity and mortality." (PMID 27115295, 2016). "This phenomenon was mirrored in a mouse model of sepsis in which we focused on IL-6 expression." (PMID 27303721, 2016). "CRP, PCT and IL-6 are used widely in attempting to clinically diagnose sepsis." (PMID 27287669, 2016). "Actually, recent meta-analysis reported a lack of association between IL-6 -174G/C polymorphism and sepsis risk." (PMID 27861595, 2016). "Proinflammatory cytokines TNF-α, IL-1β, and IL-6 are produced in the initial phase of sepsis." (PMID 27195281, 2016). "TNF-α, IL-6, and IL-1β are the main inflammatory cytokines released in sepsis, which may assess the severity of sepsis." (PMID 26904148, 2016). "The animals 18 h after CLP-induced sepsis had marked elevations in IL-1β, IL-6, TNF-α, and MCP-1." (PMID 27822777, 2016). "Furthermore, the sepsis-induced increases in tissue levels of IL-1β, IL-6, and TNF-α mRNAs were lowered when the two blockers were given together to the animals." (PMID 27822777, 2016). "We evaluated the modulation of monocyte functions during sepsis by simultaneously assessing their phagocytic activity, the generation of reactive oxygen species (ROS) and nitric oxide (NO), and the production of inflammatory cytokines (IL-6 and TNF-α)." (PMID 26879814, 2016). "Using sepsis models, we investigated the role of IL-6 in systemic inflammatory responses." (PMID 27146354, 2016). "Taken in the context of these previous reports, our findings of elevated IL-6, IL-8, and G-CSF in the setting of neutropenic sepsis suggest that the neutropenic host is primed to rapidly recruit neutrophils from the bone marrow to the peripheral tissues upon count recovery." (PMID 27431667, 2016). "Neutropenia was independently associated with a higher AKI risk and was characterized by a profile of high IL-6, IL-8, and G-CSF relative to non-neutropenic sepsis." (PMID 27431667, 2016). "Increased IL-6 was reported in patients with sepsis and leukocyte sequestration, as in our data." (PMID 26757701, 2016). "The elevatedexpression of TNF-α, IL-1β, and IL-6 is an important step in the pathogenesis of ALI andacute respiratory distress syndrome.Moreover, in the case of humans with ALI or sepsis, a persistent elevation of thesecytokines was associated with a poor prognosis." (PMID 26648090, 2016).